NAIP (NLR family apoptosis inhibitory protein)
Diseases named in the same sentence as NAIP in open-access papers (continued):
Sharing a sentence is not in itself a finding about the gene and the disease.
lymphoma (2 papers, 2012 to 2014). A malignant (clonal) proliferation of B- lymphocytes or T- lymphocytes which involves the lymph nodes, bone marrow and/or extranodal sites. "Finally, considering the required Pan-IAPs profiling for translational application of IAPs as an attractive therapeutic target, prognostic and diagnostic marker, we have elucidated the NAIP expression level in different subtypes of lymphoma." (PMID 22357131, 2012). "The M.R of NAIP expression in FL as a representative of low grade lymphoma was 0.5886 ± 0.012 while the M.R of NAIP expression in both DLBCL and ALCL as a representative of high grade or aggressive lymphoma was 0.6095 ± 0.028." (PMID 22357131, 2012). "To better understand the controversial function of NAIP, we decided to evaluate NAIP expresstion in lymphomas." (PMID 22357131, 2012). "we considered the available FL cases as a representative of other low grade NHLs as well as the available DLBCL and ALCL cases as a representative of other high grade NHLs, hoping to better understanding about main function of NAIP in Lymphoma context by evaluating the NAIP protein expression." (PMID 22357131, 2012). "Also, this study clarifies the NAIP expression level in lymphoma which is required for IAPs profiling in order to be used in potential translational applications of IAPs." (PMID 22357131, 2012). "Despite a slight increase of NAIP expression in high grade lymphoma comparing to low grade one, over expression of NAIP was not statistically significant neither in low grade nor in high grade NHLs in compression with the control group." (PMID 22357131, 2012). "NAIP expression was not statistically different in lymphoma samples neither in HL nor in NHL cases comparing to normal samples." (PMID 22357131, 2012). "But, there is no report on the possible role of NAIP in lymphoma malignancies." (PMID 22357131, 2012). "We found that the differences in expression of NAIP are not statistically significant in none of favorable (HL), low grade (FL) and even high grade (DLBCL and ALCL) types of lymphoma in comparison with non-neoplastic control group." (PMID 22357131, 2012).
muscular atrophies (2 papers, 2012 to 2017). "NAIP was originally identified while investigating childhood muscular atrophy, and was also related to spinal muscular dystrophy; it has been suggested that NAIP triggers apoptosis by inhibition of the executioner caspases-3 and -7." (PMID 28327526, 2017).
preeclampsia (2 papers, 2022 to 2023). Preeclampsia is a hypertensive disorder of pregnancy that is characterized by new-onset hypertension with proteinuria presenting after 20 weeks of gestation, and depending on mild or severe forms may initially present with severe headache, visual disturbances, and hyperreflexia. "Long noncoding RNA AK002210 improves the proliferation, migration and invasion of trophoblast cells through the regulation of NAIP expression, which is implicated in the modulation of phenotype of the trophoblast cell, as well as the progression of preeclampsia." (PMID 36560538, 2022). "Long non-coding RNA AK002210 modulates the expression of NAIP, which regulates the phenotype of the trophoblast cell, and plays a critical role in the progression of preeclampsia." (PMID 37228386, 2023).
Allergy (1 paper, 2024). An allergy is an immune response or reaction to substances that are usually not harmful. "However, to really understand the role of NLRP3 in BP allergy as well as in other allergic disorders, a cell type-specific knockout or knock-in similar to what has already been established for the NAIP/NLRC4 inflammasome would be beneficial." (PMID 38933263, 2024).
Alzheimer disease (1 paper, 2013). A progressive, neurodegenerative disease characterized by loss of function and death of nerve cells in several areas of the brain leading to loss of cognitive function such as memory and language. "In addition, IAP proteins have been associated with neurodegenerative diseases: NAIP was found to be decreased in Alzheimer disease patients, suggesting that decreased NAIP may place neurons at risk for the development of tangles and apoptosis." (PMID 24146536, 2013).
Chagas disease (1 paper, 2023). A parasitic infection caused by Trypanosoma cruzi. "In this study, we investigated the activation of the NAIP/NLRC4 inflammasome in response to Trypanosoma cruzi, the protozoan parasite responsible for causing Chagas disease." (PMID 38124741, 2023). "In this study, we demonstrated a previously unknown role of NAIP/NLRC4 inflammasome in response to the T. cruzi infection, a protozoan parasite responsible for causing Chagas disease." (PMID 38124741, 2023).
cognitive decline (1 paper, 2012). "Further, it has been suggested that a rise of the NAIP protein level protects AD patients against the development of tangle pathology and cognitive decline." (PMID 22545106, 2012).
colitis (1 paper, 2024). Inflammation of the colon. "In fact, the deletion of genes encoding NLRC4 or NAIP increased the susceptibility of mice to the development of colitis and CRC associated with colitis." (PMID 39684769, 2024). "In addition, in a Dextran Sulfate Sodium (DSS)-induced colitis mouse model, DSV and its flagellin enhanced intestinal inflammation and induced significant macrophage pyroptosis, promoting NAIP/NLRC4 inflammasome activation." (PMID 39684769, 2024).
colon cancer (1 paper, 2019). "Not only NAIP expression in colon cancer samples was found to be lower than in normal mucosa but also, based on a model of colitis-associated cancer, mice lacking NAIP paralogs (Naip1-6) display a higher susceptibility for CRC in an inflammation-independent mechanism." (PMID 30837326, 2019).
colorectal cancer (1 paper, 2020). A primary or metastatic malignant neoplasm that affects the colon or rectum. "Online databases Oncomine and GEPIA were used to compare the expression of IAPs (NAIP, BIRC2, BIRC3, XIAP, BIRC5/survivin, BIRC6 and BIRC7, no data on BIRC8 was available) between colorectal cancer and normal tissues." (PMID 32381104, 2020).
cryopyrin-associated periodic syndrome (1 paper, 2019). Cryopyrin associated periodic syndrome (CAPS) defines a group of autoinflammatory diseases, characterized by recurrent episodes of systemic inflammatory attacks in the absence of infection or autoimmune disease. "Moreover, gain-of-function mutations in and around the central NAIP, CIITA, HET-E, and TP1 (NACHT) domain of NLRP3 cause three autosomal dominantly inherited periodic fever syndromes that together are known as cryopyrin-associated periodic syndrome (CAPS)." (PMID 31525186, 2019).
enteropathy (1 paper, 2021). "In NAIP/NLRC4-deficient mice, S.Tm elicited severe enteropathy within 72 h, characterized by elevated mucosal TNF (>20 pg/mg) production from bone marrow-derived cells, reduced regeneration, excessive enterocyte loss, and a collapse of the epithelial barrier." (PMID 33731826, 2021).
HIV-1 infection (1 paper, 2021). The type species of lentivirus and the etiologic agent of acquired immunodeficiency syndrome (AIDS). "Thus, NAIP associated with gp41 only in the presence of an HIV-1 infection." (PMID 33861800, 2021). "The STORM data demonstrated that NAIP–gp41 complexes colocalize with NLRC4 providing further evidence that upon HIV-1 infection, gp41 forms clusters with NAIP and NLRC4 where it triggers inflammasome activation leading to IL-18 secretion." (PMID 33861800, 2021).
Miscarriage (1 paper, 2023). A pregnancy that ends at a stage in which the fetus is incapable of surviving on its own, defined as the spontaneous loss of a fetus before the 22th week of pregnancy. "In women who experienced miscarriage, low NAIP expressions may suggest a lower cell survival capacity and a greater tendency to apoptosis." (PMID 36768802, 2023).
myasthenia (1 paper, 2016). "This patient was first hospitalized due to pneumonia and myasthenia when he was 1 month old in May 2013, who was homozygous for the SMN exon 7 deletion, and the remaining 1999 samples were negative for SMN, NAIP and GTF2H2 deletion." (PMID 27534852, 2016).
myocardial infarction (1 paper, 2015). Gross necrosis of the myocardium, as a result of interruption of the blood supply to the area, as in coronary thrombosis. "For example, miR-1 has been reported to be downregulated in various CVDs including myocardial infarction (MI), and it is predicted to target multiple NLR proteins (NOD1, NLRP14, and NAIP)." (PMID 26491223, 2015).
Parkinson disease (1 paper, 2018). A progressive degenerative disorder of the central nervous system characterized by loss of dopamine producing neurons in the substantia nigra and the presence of Lewy bodies in the substantia nigra and locus coeruleus. "Moreover, we examined the MNC-NAIP levels in Japanese with Parkinson’s disease, and the NAIP level in MNC from Parkinson’s disease patients was as high as that of healthy controls (average, 0.91 ± 0.46 ng/μg)." (PMID 29311650, 2018). "Accordingly, we identified the NAIP-upregulated small molecule compound L-745,870 as a drug candidate for antipsychotic treatment, bromocriptine mesylate (BRC) as a Parkinson’s disease drug, and WN1316 as a drug candidate for ALS24–27." (PMID 29311650, 2018).
pneumonia (1 paper, 2016). An acute, acute and chronic, or chronic inflammation focally or diffusely affecting the lung parenchyma, caused by an infection in one or both of the lungs (by bacteria, viruses, fungi, or mycoplasma.). "There was a much lower survival rate in patients with a homozygous deletion in NAIP or GTF2H2 (p < 0.01), particularly in the first 2 months after suffering from pneumonia." (PMID 27534852, 2016).
prostate tumor (1 paper, 2014). "In studies reported here, the NAIP gene was significantly down-regulated in human prostate tumor cells treated in vitro and in vivo with enzalutamide." (PMID 25344864, 2014). "The reduction of NAIP was not seen in AR− PC-3 prostate tumors, further confirming that immunogenic modulation by enzalutamide is strictly dependent upon AR expression." (PMID 25344864, 2014).
infection (25 papers, 2010 to 2025). The state of being infected such as from the introduction of a foreign agent such as serum, vaccine, antigenic substance or organism. "This appeared remarkably similar to the day 3 infection phenotypes previously seen in NAIP/NLRC4-deficient mice." (PMID 37988464, 2023). "To confirm association of NLRP3, NLRC4 and NAIP with ASC during CFT073 infection of THP-1m, we performed immunoprecipitation of ASC and detected NLRP3, NLRC4 and NAIP proteins." (PMID 31551961, 2019). "The inflammasome molecules AIM2, NLRP3, NLRP6 and NLR Family Apoptosis Inhibitory Protein (NAIP)/NLRC4 were reported to play important roles in epithelial cells by protecting against infection and maintaining tissue homoeostasis." (PMID 37365163, 2023). "Their study elaborated that high expression of NAIP is sufficient to activate the inflammasome in response to infection under physiological conditions." (PMID 36817458, 2023). "Given the central role of NAIP/NLRC4 inflammasomes in controlling infection and, also, induction of inflammatory pathologies, many efforts have been made to uncover novel molecules involved in their regulation." (PMID 36481780, 2022). "Our data confirm that both NLRP3 and NAIP/NLRC4 contribute to the inflammasome response in human macrophages upon infection with S. Typhimurium, but the relative contribution of various ligands of this bacterium is unclear." (PMID 33380493, 2021). "By imaging infections in 3D-, 2D-, and chimeric enteroids, we mapped NAIP/NLRC4-driven cell death features in both space and time." (PMID 33731826, 2021). "To clarify this aspect, we assessed the expression of NAIP-activating S. Tm PAMPs during the infection process." (PMID 31953493, 2020). "A clear upregulation of NLRC4 and NAIP in THP-1m upon CFT073 infection was seen as compared to resting macrophages (mock)." (PMID 31551961, 2019). "NAIP/NLRC4 are most likely the best-studied inflammasomes in the context of host resistance against infections." (PMID 25071770, 2014). "Although it has been shown that a PrgJ homolog, from the bacterium Chromobacterium violaceum, is specifically recognized by human NAIP, further studies are required to determine the importance of human NAIP during infection with common bacterial pathogens." (PMID 24155747, 2013). "Concomitant animal infection studies from two different groups showed that the specificity of the NLRC4 inflammasome is determined by different NAIP paralogs." (PMID 24155747, 2013). "Notably, WT and NAIP-/- cells pretreated with glycine exhibited significantly decreased cell death and a small defect in IL-1β release following infection compared to infected cells treated with the vehicle control." (PMID 40162563, 2025). "In these Nlrc4−/− mice, which cannot control epithelial S. Tm loads, increased lamina propria TNF-α levels drive barrier dislodgement by day 3 post infection, indicating that the NAIP/NLRC4 inflammasome is also required to prevent late-stage barrier disruption." (PMID 40796289, 2025). "The significance of NLCR4/NAIP has been demonstrated in Nlrc4−/− mice, which show 50-fold higher S. Tm loads in the caecum tissue compared to Nlrc4+/− littermate controls at 18 h post infection." (PMID 40796289, 2025). "First, to determine whether glycine exerts a cytoprotective effect on THP-1 macrophages, we pretreated WT and NAIP-/- THP-1 cells with glycine prior to infection with WT Salmonella and assayed for downstream inflammasome responses." (PMID 40162563, 2025). "Both GSDMD and NAIP/NLRC4 limit S.Tm loads in the deeper gut mucosal tissue, as well as in systemic organs, and prevent the loss of epithelial barrier integrity by 48 to 72 h of infection." (PMID 37988464, 2023). "In addition to the direct binding of bacterial ligands by NAIP proteins, other regulatory mechanisms participate in NAIP/NLRC4 activation under infections or sterile condition." (PMID 36481780, 2022).
infection (continued). "It remained unknown how this NAIP/NLRC4-dependent tradeoff would develop during subsequent infection stages." (PMID 33731826, 2021). "Our work uncovers a central role of epithelium-autonomous NAIP/NLRC4 in eliciting a fine-tuned early response to the infection, thereby preventing the demise of the epithelial barrier, due to an overshooting pro-inflammatory TNF response in the intestinal mucosa." (PMID 33731826, 2021). "Notably, the restriction of systemic bacterial loads by epithelial NAIP/NLRC4 was equally relevant in an infection with a different S. Tm strain (S. Tm14028)." (PMID 31953493, 2020). "Therefore NAIP/NLRC4 inflammasomes are considered to be crucial regulators of infection and immunity." (PMID 32630319, 2020). "These effector mechanisms mediated by NAIP/NLRC4 inflammasomes have been extensively studied in the context of resistance of infections and the potential of their agonists has been exploited in therapeutic strategies to non-infectious pathologies, such as tumor protection." (PMID 25071770, 2014). "Although the possible targets of caspase-1 and caspase-11 mobilized during pyroptosis remain unidentified, the studies involving NAIP/NLRC4 hugely contribute to the idea that this inflammatory form of cell death is an important effector mechanism against infections." (PMID 25071770, 2014). "Similar to the NAIP/NLRC4 inflammasome, GSDMD is required for the protection against infection of IECs at 18 h post infection." (PMID 40796289, 2025). "For example, studies employing wild-type S. Tm infections showed that the epithelial NAIP/NLRC4 inflammasome and downstream effectors (e.g., GSDMD) are crucial for preventing destructive inflammation in 72 h S. TmWT infection." (PMID 41370284, 2025). "We find that although the NAIP/NLRC4 inflammasome is essential for detecting T3SS ligands in human macrophages, it is partially required for responses to infection, as Salmonella also activated the NLRP3 and CASP4/5 inflammasomes." (PMID 35073381, 2022). "Rather, we found that infection of human macrophages with Salmonella grown under SPI-1-inducing conditions activates multiple inflammasomes, including NAIP/NLRC4, CASP4/5, and NLRP3." (PMID 35073381, 2022). "Conversely, NAIP/NLRC4 in phagocytes is dispensable for the restriction of Salmonella dissemination and replication at infection sites during early infection." (PMID 35888979, 2022). "At 6 or 24 hours post-infection, the bacterial burden was the lowest in WT THP-1s, whereas NAIP-/- and NLRC4-/- THP-1s harbored significantly higher bacterial burdens." (PMID 35073381, 2022). "The bacterial burden of ΔprgIfliCfljB over a 24-hour post-infection time course was controlled the most effectively in WT THP-1s and was significantly less restricted in NAIP-/- and NLRC4-/- THP-1s." (PMID 35073381, 2022). "In human and murine macrophages, NAIP/NLRC4 and NLRP3 are triggered to form inflammasomes upon infection with S. Typhimurium." (PMID 33380493, 2021). "In THP-1 cells, NAIP/NLRC4 and NLRP3 played redundant roles in inflammasome activation during infection with S. Typhimurium." (PMID 33380493, 2021). "In sharp contrast, our analysis proves phagocyte NAIP/NLRC4 to be dispensable for restriction of S. Tm migration to, and replication at, systemic sites during early infection." (PMID 31953493, 2020). "Until now, the primary role attributed to the NAIP/NLRC4 inflammasome has been its activation in triggering the inflammatory response of the host, thereby contributing to defense against infection by limiting bacterial proliferation within infected cells, predominantly macrophages." (PMID 40158217, 2025). "Additionally, there is downregulation in the expression of apoptosis inhibiting genes like NAIP and BCL2A1 following infection." (PMID 39287214, 2024).